RPA1 (replication protein A1)
Diseases named in the same sentence as RPA1 in open-access papers (continued):
Sharing a sentence is not in itself a finding about the gene and the disease.
cancer (100 papers, 2006 to 2026). A tumor composed of atypical neoplastic, often pleomorphic cells that invade other tissues. "We discovered significant enrichment of ultra-rare and novel RPA1 germline variants in our pediatric cancer cohort compared to non-cancer controls, positioning RPA1 as a novel candidate predisposition gene." (PMID 37869077, 2023). "Taken together, these findings suggest that germline putative damaging variants affecting RPA1 are found in excess in children with cancer, warranting further investigation into the functional role of these variants in oncogenesis." (PMID 37869077, 2023). "We found that ultra-rare and novel germline variants in the RPA1 gene were significantly more common among pediatric cancer patients than non-cancer controls." (PMID 37869077, 2023). "Although ultra-rare and novel heterozygous germline variants in RPA1 were significantly enriched in pediatric cancers, it is difficult to ascertain pathogenicity and clinical relevance without functional follow-up, which falls beyond the scope of this study." (PMID 37869077, 2023). "We plan to exploit our findings and perform further functional and biochemical characterization of recurrent cancer associated RPA1 variants to assess their potential use as targets for future cancer therapies." (PMID 37869077, 2023). "Within the pan-cancer cohort, we identified 80 cases with 55 germline heterozygous RPA1, RPA2 or RPA3 variants meeting criteria of AF < 0.5% in gnomAD non-cancer cohort and CADD score > 15 for candidate variant selection." (PMID 37869077, 2023). "RPA1 degradation is prominently observed in cancer cells and is associated with BMH-21-induced cancer cell death." (PMID 36497261, 2022). "Nevertheless, mice bearing a semi-dominant heterozygous mis-sense mutation in Rpa1 (Rpa1L230P) exhibit gross genomic rearrangements and are highly cancer prone (Rpa1L230P homozygosity is cell lethal)." (PMID 21901111, 2011). "Moreover, we have identified enrichment of RPA1 variants in cancer cases compared to non-cancer controls, suggesting that this gene potentially acts as a novel cancer driver." (PMID 37869077, 2023). "We speculate that germline RPA1 alterations may be more common in human disease, given that somatic RPA1 mutations occur in ~1% of cancers." (PMID 34633564, 2021). "Notably, early studies of the GEMINI genes POLR2A and RPA1 achieved allele-specific growth suppression of cancer cells using ASO4,61,62 and RNAi63 reagents." (PMID 32433464, 2020). "Furthermore, forced over-expression of RPA1 can cause genomic instability, at least in cancer cell lines." (PMID 21901111, 2011). "Although still in the preliminary stages, these insights offer a promising framework for future studies exploring the molecular mechanisms of RPA1-dependent ETAA1 in cancer interventions." (PMID 39660144, 2024). "Inhibitors specifically targeting the PPI or the ssDNA-binding activity of human RPA1 are being developed as anti-cancer therapeutic candidates." (PMID 37474515, 2023). "To address this knowledge gap, we investigated the occurrence of novel and rare germline variants in RPA1, RPA2 and RPA3 genes, in a cohort of 5,993 children with cancers." (PMID 37869077, 2023). "By mining the Catalogue Of Somatic Mutations In Cancer (COSMIC) database, we found that somatic mutations in RPA1, RPA2, RPA3 are found in 1.4%, 0.5%, and 0.9% of human cancers, respectively." (PMID 37869077, 2023).
cancer (continued). "Several laboratories have developed RPA1 inhibitors for cancer therapy by targeting specific functions of RPA129–38." (PMID 37474515, 2023). "We also showed that FBXL14 overexpression activated RPA1 turnover in cancer cell lines that were resistant to this degradation." (PMID 36497261, 2022). "RPA plays a role in the replication of DNA, and it has been found that miR-30a hinders the replication of DNA and induces DNA fragmentation by targeting RPA1 and then slows cancer cell proliferation." (PMID 30158978, 2018). "Therefore, we began our investigation with a pan-cancer screening of RPA1 using TCGA data, which revealed a significant up-regulation of RPA1 in liver hepatocellular carcinoma (LIHC) compared to adjacent normal tissue controls (p<0.001)." (PMID 39660144, 2024). "Overexpression of KILR mimics the reported effects of RPA1 knockdown on cancer cell growth." (PMID 38745269, 2024). "Based on these data, we reasoned that germline defects in RPA1 and possibly also the other 2 components of the RPA heterotrimer (RPA2 and RPA3) might be associated with cancer development." (PMID 37869077, 2023). "We discovered 1.05% (63/5993) of the cohort to harbor heterozygous germline RPA1 variants, which was statistically not significant compared to gnomAD non-cancer controls for all cancers and cancer subtypes." (PMID 37869077, 2023). "Compared with Genome Aggregation Database (gnomAD) non-cancer controls, there was significant enrichment of ultra-rare and novel RPA1, but not RPA2 or RPA3, germline variants in our cohort (adjusted p-value < 0.05)." (PMID 37869077, 2023). "Overexpressed RPA1 and/or RPA2 are detected in various cancers, suggesting that RPA may be useful as a prognostic marker in cancer patients." (PMID 34316690, 2020). "Congenitally elevated genomic instability is often associated with cancer predisposition, although this has not been noted in either 17p13.3 duplication syndrome patients associated with RPA1-duplication." (PMID 21901111, 2011). "In conclusion, our research reveals that HAT1-regulated RPA1 lactylation plays an important role in homologous recombination and radioresistance, suggesting that HAT1 may become a potential therapeutic target for reversing the radioresistance caused by lactate accumulation in cancer cells." (PMID 41271679, 2025). "While the role of CDYL2 in malignant tumors is scarcely documented, CDYL (chromodomain Y like), a member of the CDYL family, has been reported to govern the post-translational modification of RPA1, thereby influencing HR repair." (PMID 38654320, 2024). "The remaining shared hits in the 5 cancer cell lines included X-Ray Repair Cross Complementing 1 (XRCC1), PARP1, Replication Protein A1 (RPA1) and DNA ligase 3 (LIG3)." (PMID 36386669, 2022). "Cancer growth can also be reliant on high expression of specific E2 cell cycle target genes including AURKA, KIF4A, STAG1, CTCF, and RPA1, all of which were identified highly expressed in at least one of the at-risk samples studied here." (PMID 35459280, 2022). "A way to modulate RPA–protein interactions in cancer cells, and thereby to disrupt DDR activation, is via specific inhibitors that target the N-terminus or RPA1 (70N) and the C-terminus of RPA2 (32C), which harbor the protein interaction modules." (PMID 34316690, 2020). "The RPA (human replication protein A) family, including RPA1, RPA2, and RPA3, plays an essential role in eukaryotic DNA replication, homologous recombination, and excision repair; it has been recognized as an oncogene and therapeutic target for cancer." (PMID 37091868, 2023). "However, in numerous cancers including CRC, RPA1 mRNA and/or protein expression is significantly increased and associated with a poor prognosis in advanced cancer patients and known to stimulate proliferation of cancer cells." (PMID 34382747, 2021).
cancer (continued). "Rpa1 and Crk were not appealing as candidates: Rpa1 showed only a rather moderate down regulation in gene expression analysis and Crk (v-crk sarcoma virus CT10 oncogene homolog, avian) is mainly recognized as an oncogene in cancer studies." (PMID 26170120, 2015).
tumor (51 papers, 2011 to 2026). "In Luminal B tumours, low RPA1 was associated with shorter BCSS (P = 0.019) and DMFS (P = 0.029)." (PMID 36997566, 2023). "A more recent exome-wide association study of 31,870 common SNPs involving 5553 patients with NPC has also identified a novel germline polymorphism in RPA1 (rs1131636) conferring tumor progression and therapeutic resistance in NPC, which ultimately affects the patient’s survival." (PMID 35954343, 2022). "With the bioinformatic analyses and biological evidence in current study, we identified a novel germline polymorphism of RPA1 gene (rs1131636) conferring tumor progression and therapeutic resistance in NPC, which ultimately affects the survival of patients with NPC." (PMID 32440486, 2020). "The IHC results confirmed that RPA1 proteins were highly expressed in tumor tissues compared to adjacent normal tissues." (PMID 40593477, 2025). "RPA1 is key to maintaining genomic stability and regulating tumor cell responses to genotoxic stress from treatments like chemotherapy or radiation." (PMID 39660144, 2024). "Among the selected genes, only RPA1, MCM5 and FEN1 had significantly (p < 0.05; q < 0.05) higher mRNA expression in BRAFV600E-mutated tumor samples in comparison with unaltered group." (PMID 37106808, 2023). "We previously determined that RPA1 increases tumor growth and resistance to therapeutics in NPC, which affects the prognosis for individuals with NPC, using bioinformatic investigations and biological evidence." (PMID 37858134, 2023). "We further demonstrated the functional relevance of RPA1 on tumor aggression and radioresistance as well as the mechanism of the germline SNP involved in regulating RPA1 expression." (PMID 32440486, 2020). "To further validate this finding, we examined the mRNA expression of RPA1 in a subset of primary‐recurrent tumor pairs." (PMID 32440486, 2020). "The study also shows that RPA1 is able to regulate tumor progression and radioresistance in NPC cells." (PMID 32440486, 2020). "PTEN functions as a tumor suppressor that localizes to replication sites and physically interacts with the RPA1 C-terminus." (PMID 34316690, 2020). "On the other hand, the important role that RPA1 plays in maintaining the stability of the genome makes this gene a candidate for tumor suppressors." (PMID 32849834, 2020). "Other studies report tumor suppression mechanisms that involve the regulation of RPA1 during DNA replication by PTEN." (PMID 34316690, 2020). "Importantly, significant associations between RPA1, ETAA1 and PD-L1 were identified (p<0.001), with these connections being specific to the tumor context." (PMID 39660144, 2024). "Suppression of the POLQ, PRIM1 and RPA1 genes increased the radiosensitivity of tumour cells, while overexpression conferred increased resistance.Therefore, these genes could be potential therapeutic targets to improve the efficacy of radiotherapy." (PMID 39132508, 2024). "Interestingly, pseudogene expression (34%) and lncRNA/novel transcripts expression (34%) was higher in RPA1 low tumours compared to RPA1 high tumours (11% and 24%, respectively)." (PMID 36997566, 2023). "Low RPA1 mRNA was significantly associated with shorter overall survival in the whole cohort (P = 0.024), in ER + tumours (P = 0.01) but not in ER- tumours (P = 0.47)." (PMID 36997566, 2023). "In IBC, low RPA1 was observed in 55% (1147/2083) of tumours." (PMID 36997566, 2023). "In vivo xenograft model revealed that the shRPA1 xenografts with RPA1 knockdown cells had reduced tumor volume and weight, as compared to the control group, indicating that the knockdown of RPA1 significantly inhibited orthotopic tumor formation of NPC cells in mice." (PMID 32440486, 2020). "Three patients had germline variants of uncertain significance (ACMG Class 3) in FANCG, RAD51B, and RPA1, respectively, whose allele frequencies were not increased in the tumor compared with the normal control sample." (PMID 30967556, 2019).
tumor (continued). "Previous reports have shown that the overexpression of CDT1 and depletion of RPA1 could increase the activation of origin, induce DNA damage, stalled fork replication, defects in DNA damage repair, and promote genomic instability during tumor development." (PMID 34893582, 2021). "For example, RPA1 may act as a tumor suppressor in the PTEN signaling pathway." (PMID 32849834, 2020). "Further investigations revealed that knockdown of the TFs candidates—DDB1, PARP1, XRCC5, RPA1, and RPA3—resulted in a significant reduction in tumor sphere formation." (PMID 40230524, 2025). "In this regard, the main targeting components of DNA repair machinery such as RAD51, XRCC3, RPA‐1 in HR and XRCC4, KU70, KU80 in NHEJ can open a new window for treatment of the EC by sensitizing tumor cells to radiotherapy." (PMID 36147024, 2022). "Previous studies found that miR-1293 inhibited the growth of tumor cells by simultaneously targeting BRD4, APEX1, RPA1, and POLD4 via inhibiting the DNA repair pathway." (PMID 36147635, 2022). "Given the observations that radiosensitization through incremental DNA damage on tumor cells is highly related to NPC remission, we performed clonogenic assays to investigate if manipulating RPA1 has any effect on the radiosensitivity of NPC cells." (PMID 32440486, 2020). "Therefore, it is plausible that the favorable outcomes of NPC patients with CC‐genotype may be linked to increased tumor radiosensitivity and less aggressiveness due to reduced RPA1 expression, as opposed to patients with the CT or TT genotype." (PMID 32440486, 2020). "In the current study, we found that the five differential expression genes (NFBD1, BRCA1, BRCA2, RPA1 and RAD51) were involved in NPC radioresistance, which was further validated in CNE2-RR cells, tumor xenografs and NPC patients." (PMID 32015678, 2020). "Seven genes out of 13 (CCNH, ERCC2, ERCC6, NEIL1, OGG1, RPA1, XPA) had a significantly different expression in tumour versus normal tissue stored in PAXgene Tissue System." (PMID 27383461, 2016). "Notably, both RPA1 and CDK4 mRNA levels were elevated in tumor tissues relative to adjacent normal tissues." (PMID 40593477, 2025). "In addition, we analysed the gene expression data of HNSC cases in the TCGA data set, which suggested that RPA1 and RPA3 were up‐regulated in HNSC tissues compared with non‐tumour tissues, whereas RPA2 expression did not significantly differ between HNSC and non‐tumour tissues." (PMID 28557284, 2017).
infection (20 papers, 2008 to 2026). The state of being infected such as from the introduction of a foreign agent such as serum, vaccine, antigenic substance or organism. "RPA1 associates with input viral genomes early during infection and remains associated throughout infection." (PMID 30018111, 2018). "Early during infection, viral genomes also associate with factors that have known roles in the recognition or processing of DNA breaks, including RPA1, PARP1, PARP14, and ligase 3 (LIG3)." (PMID 30018111, 2018). "An interesting observation from these studies is that at least 4× more RPA1 associates with input viral genomes throughout the course of infection compared to replicated viral DNA and 9× more associates with n12 input genomes compared to replicated wild-type viral DNA." (PMID 30018111, 2018). "RPA1 has been shown to be recruited to HSV-1 and human cytomegalovirus genomes during infection and is sometimes associated with a subset of PML NBs." (PMID 30018111, 2018). "Consistent with its potential role in DDR during infection, our previously published SIRT2 interactome identified many DNA damage sensor and repair proteins including KU70/KU80, RPA1, FEN1 and PARP1." (PMID 34929015, 2021).
CNS tumors (1 paper, 2023). "Statistical analysis using two- and one-sided Fisher exact tests of ultra-rare plus novel and rare germline heterozygous variants in RPA1, RPA2 and RPA3 across hematologic, extra-cranial solid and CNS tumors." (PMID 37869077, 2023).
hematological malignancies (1 paper, 2023). "Germline heterozygous variants found in RPA1, RPA2 and RPA3 in pediatric hematological malignancies." (PMID 37869077, 2023).
RPA1 also shares sentences with these, for which no sentence is quoted: Fanconi anemia (14 papers); osteosarcoma (6); xeroderma pigmentosum (5); virus infection (3); xeroderma pigmentosum group C (3); Autoimmunity (2); brain tumors (2); infectious disease (2); lung adenocarcinoma (2); melanoma (2); neurodegenerative disease (2); spinocerebellar ataxia type 1 (2); Werner syndrome (2); xeroderma pigmentosum group A (2); acrofacial dysostosis (1); acute myeloid leukemia (1); acute myocardial infarction (1); adenovirus infection (1); autism spectrum disorder (1); bacteremia (1); Bloom syndrome (1); bone osteosarcoma (1); breast tumor (1); cyst (1); dermatomyositis (1); developmental delay (1); diffuse large B-cell lymphoma (1); ductal carcinoma in situ (1); dysplasia (1); endometrial cancer (1).
A further 44 diseases each share a sentence with RPA1 in 1 paper.